CENPO (centromere protein O)
Diseases named in the same sentence as CENPO in open-access papers:
CENPO is named in the same sentence as 27 diseases in open-access papers, as found by Europe PMC text mining. Sharing a sentence is not in itself a finding about the gene and the disease. The quoted sentences say what the papers report.
gastric cancer (5 papers, 2022 to 2024). A primary or metastatic malignant neoplasm involving the stomach. "High CENPO expression promotes the proliferation of gastric cancer cells and is positively associated with poor prognosis in gastric cancer." (PMID 37558987, 2023). "Recent studies have shown that the alteration of CENPO expression can mediate the proliferation of gastric cancer cells." (PMID 35201521, 2022).
breast carcinoma (4 papers, 2016 to 2023). "Recent studies have demonstrated that breast cancer patients with high CENPO expression have a poor prognosis and are independent factors affecting the distant recurrence–free survival (DRFS) of breast cancer patients." (PMID 37558987, 2023). "TYMS physically interacts with two genes from the HER2 pattern -CENPO and CENPA and is a target gene of three Breast cancer drugs (Fluorouracil, Capecitabine and Gemcitabine)." (PMID 26892392, 2016).
colorectal cancer (3 papers, 2022 to 2023). A primary or metastatic malignant neoplasm that affects the colon or rectum. "CENPO can prevent the separation of sister chromatids and cell death after spindle injury, and may play a promoting role in colorectal cancer through the epithelial mesenchymal transition (EMT) and PI3K/AKT signaling pathway." (PMID 37061713, 2023).
lung adenocarcinoma (2 papers, 2023). A carcinoma that arises from the lung and is characterized by the presence of malignant glandular epithelial cells. "We found that CENPO was significantly upregulated in multiple cancers and correlated with lung adenocarcinoma (LUAD) staging, overall survival (OS), and DFS." (PMID 37558987, 2023). "Here, we assessed the function of CENPO in pan-cancer and further verified the results in lung adenocarcinoma (LUAD) through in vitro and in vivo experiments." (PMID 37061713, 2023). "Here, we investigated the role of CENPO in pan–cancer and further validated its role in lung adenocarcinoma (LUAD) by in vitro experiments." (PMID 37558987, 2023).
thyroid cancer (2 papers, 2023). "In contrast, CENPO was downregulated in thyroid carcinoma (THCA) and kidney chromophobe (KICH)." (PMID 37061713, 2023). "However, CENPO was downregulated in renal cell carcinoma (KICH), and thyroid cancer (THCA)." (PMID 37558987, 2023).
adrenocortical carcinoma (1 paper, 2023). "CENPO was significantly associated with the stage of adrenocortical carcinoma (ACC), BRCA, KICH, KIRP, LIHC, LUSC, OV and LUAD." (PMID 37061713, 2023).
lung carcinoma (1 paper, 2023). "Our screening results showed that the IC50 of 114 drugs correlated with the expression of CENPO (P < 0.001), 15 of which were clinically used lung cancer therapeutics." (PMID 37558987, 2023).
ovarian carcinoma (1 paper, 2024). A malignant neoplasm originating from the surface ovarian epithelium. "Significantly increased CENPO mRNA levels were observed in cancer tissues when compared with paired normal tissues (P < 0.0001).To confirm these results, we used qPCR to examine the expression levels of CENP-O across five different ovarian cancer cell lines against normal ovarian cell lines IOSE80." (PMID 38890751, 2024).
uterine carcinoma (1 paper, 2023). A carcinoma involving a uterus. "CENPO alteration was observed in 32 cancers, of which uterine carcinoma had the highest incidence rate of 5.34%." (PMID 37061713, 2023).
viral infection (1 paper, 2023). "Therefore, studying CENPO can help uncover the molecular mechanisms of viral infection and provide insights for the development of antiviral drugs." (PMID 37896902, 2023). "Additionally, the function of CENPO in cell cycle regulation may have implications for viral infections." (PMID 37896902, 2023).
tumor (8 papers, 2021 to 2024). "This suggested that high CENPO expression was associated with decreased infiltration of immune and stromal cells in several tumors, thereby resulting in high tumor purity." (PMID 37061713, 2023). "Moreover, the expression of CENPO was closely related to the expression of tumor mutational load and microsatellite instability." (PMID 37558987, 2023). "Furthermore, CENPO has been implicated in immune cell infiltration in pan-cancer and represents a potential immunotherapeutic target for tumor therapy." (PMID 37061713, 2023). "The relationship between CENPO expression and immune cell varies greatly in each type of tumor depending on the type of immune cell." (PMID 37061713, 2023). "Subsequently, loss-of-function assays were performed to identify the functions of CENPO on the malignant behavior and tumor growth of LUAD in vitro and in vivo experiments." (PMID 37061713, 2023). "The results suggested that CENPO expression was significantly positively correlated with tumor grade." (PMID 35201521, 2022). "We found that the proportion of high expression of CENPO in tumor tissues of CRC patients was significantly higher than that of normal tissues (P < 0.001)." (PMID 35201521, 2022). "CENPO was not only highly expressed in tumor tissues, but also positively correlated with the deterioration of CRC patients." (PMID 35201521, 2022). "The signal intensity of CENPO, Ki67, AKT and p-AKT in the tumor tissue after CENPO knockdown was reduced." (PMID 35201521, 2022). "Taken together, CENPO expression was not only highly expressed in tumor tissues, but also positively correlated with the deterioration of CRC patients." (PMID 35201521, 2022). "Pearson correlation further indicated that the increased expression of CENPO predicted the deepening of tumor malignancy." (PMID 35201521, 2022). "Subsequently, we performed IHC staining in the normal and tumor tissues of clinical CRC patients to further clarify the expression of CENPO in CRC." (PMID 35201521, 2022). "Consistently, the typical images of IHC staining showed a higher signal intensity of CENPO in tumor tissue than the normal tissue." (PMID 35201521, 2022). "In summary, CENPO plays a vital role in immune infiltrates in pancancer and might act as a novel immunotherapy target in tumor therapy." (PMID 37061713, 2023). "After CENPO knockdown, the average weight of tumor decreased obviously." (PMID 37061713, 2023). "Moreover, Mann–Whitney U analysis indicated that there was a significant positive correlation between the CENPO expression and tumor stage (P = 0.001)." (PMID 37061713, 2023). "Functional enrichment and pathway analysis were then performed, and correlations with immune cell infiltration, tumor mutational load (TMB), microsatellite instability (MSI), and gene methylation were investigated to understand further the biological mechanisms of CENPO in the pathogenesis of LUAD." (PMID 37558987, 2023). "Pearson correlation analysis further suggested that the high expression of CENPO may predict the deterioration of LUAD patients that the higher the tumor stage, the higher the proportion of patients with high levels of CENPO." (PMID 37061713, 2023). "CENPO is highly expressed in CRC (Colorectal Cancer) tissues and cells as positively associated with the malignancy of CRC degree and positively correlated with tumor progression possibly through EMT and PI3K/AKT signaling pathways." (PMID 37558987, 2023). "In addition, a notable increase in CENPO expression in 23 types of cancer, respectively, in paired tumor samples compared to the corresponding normal samples." (PMID 37061713, 2023). "However, the correlation between CENPO and the tumor proteins mentioned in the text required further experimental verification." (PMID 35201521, 2022). "In vivo experiments further confirmed that CENPO downregulation attenuated tumor growth." (PMID 35201521, 2022). "We found that expression of CENPO was highly expressed in tumor tissues of CRC patients." (PMID 35201521, 2022).
tumor (continued). "Moreover, the relationship between CENPO expression level and tumor characteristics of CRC patients was characterized by Mann–Whitney U." (PMID 35201521, 2022). "SE-associated CENPO was highly expressed in LUAD and positively correlated with the tumor stage, which could promote carcinogenesis and progression by regulating the cell cycle and tumor immune microenvironment." (PMID 38681203, 2024). "Tumor microenvironment score (TME score) showed that StromalScore, ImmuneScore, and ESTIMATEScore were higher in the CENPO low expression group than in the CENPO high expression group." (PMID 37558987, 2023). "Based on the information of 51 normal and 635 tumor samples from CRC patients in The Cancer Genome Atlas (TCGA) database, the differential expression of CENPO was analyzed." (PMID 35201521, 2022). "Furthermore, the expression of CENPO, Ki67, AKT and p-AKT was detected by IHC staining in mouse tumor tissues of shCENPO group and shCtrl group." (PMID 35201521, 2022). "CENPO has a positive correlation with Tregs in the TME of HCC, and high expression of CENPO increases the content of Tregs, which can be consumed to make the tumor produce anti immunity or immune escape, and promote the development of HCC." (PMID 36107579, 2022). "Meanwhile, our in vitro experiments also suggest that the knockdown of CENPO may significantly suppress the proliferation abilities of A549 and HCI-H1299 cells, and induced G2/M arrest and apoptosis, which was further confirmed using a subcutaneous xenograft tumor model in vivo." (PMID 37061713, 2023). "From the analysis of CENPO expression in 58 pairs of paired samples with complete data of cancer versus paraneoplastic tissues in LUAD, it could be concluded that the expression of CENPO was significantly higher in tumor tissues of LUAD patients than in normal tissues." (PMID 37558987, 2023).
cancer (6 papers, 2022 to 2025). A tumor composed of atypical neoplastic, often pleomorphic cells that invade other tissues. "PTPRU, IKBKE, STYK1, and CENPO are implicated in key biological pathways relevant to cancer biology, including cell signaling, cell migration, and inflammation, further supporting their relevance in tumorigenesis." (PMID 39684488, 2024). "To further investigate the mechanisms underlying the aberrant expression of CENPO in various cancers, we analyzed the relationship between CENPO expression and genomic methylation." (PMID 37558987, 2023). "We then analyzed the associated between CENPO and the functional states of 18 cancer using single cell sequence data in CancerSEA." (PMID 37061713, 2023). "Subsequently, we evaluated the diagnostic value of CENPO in multiple types of cancers using ROC curves." (PMID 37061713, 2023). "CENPO is highly expressed in most cancers, and the upregulation of CENPO is associated with poor prognosis in many cancers." (PMID 37558987, 2023). "The potential value of CENPO as a diagnostic and prognostic biomarker for pan–cancer was evaluated using TCGA data and the GEPIA database." (PMID 37558987, 2023). "ROC diagnostic curves were drawn based on the median CENPO expression of 33 cancers, which were divided into high and low expression groups." (PMID 37558987, 2023). "Furthermore, we analyzed the association between the CENPO mutation and the clinical outcomes of different cancers." (PMID 37061713, 2023). "We analyzed the diagnostic value of CENPO in various cancers using ROC curves." (PMID 37558987, 2023). "In most cancers, CENPO was upregulated and mutated, which predicted a poorer prognosis." (PMID 37061713, 2023). "We downloaded 33 pan-cancer data from the TCGA database and performed CENPO differential expression analysis and survival analysis, taking the intersection of cancers with differential CENPO expression and cancers with significantly associated OS to obtain four cancers, KICH, LIHC, READ, and SARC." (PMID 37558987, 2023). "However, little is known about how CENPO expression is associated with human cancers or immune infiltration." (PMID 37061713, 2023). "ROC curve analysis indicated that CENPO might serve as a pan–cancer diagnostic biomarker." (PMID 37558987, 2023). "In recent years, investigations into the role of the centromere protein O (CENP-O) in cancer pathogenesis have garnered substantial attention." (PMID 38890751, 2024). "The clinicopathological characteristics of these four cancers and the expression of CENPO were then subjected to COX regression analysis, which showed that CENPO and Stage were independent risk factors for KICH." (PMID 37558987, 2023). "The expression of CENPO showed a positive correlation with ICP genes in most cancers, such as UVM, KICH, KIRP, KIPANKIRC, GBM, HNSC, and BRCA." (PMID 37061713, 2023). "This research aimed to investigate the correlation between CENPO expression and immunity and visualize its prognostic landscape in pan-cancer, especially in LUAD." (PMID 37061713, 2023). "In this study, we verified that CENPO was significantly highly expressed in most cancer tissues and correlated with the TNM stage by the TCGA database." (PMID 37558987, 2023). "MSI or MATH to determine if CENPO was a predictor of immunotherapeutic responses in multiple cancer types." (PMID 37061713, 2023). "Sangerbox and TCGA databases were used to evaluate the CENPO expression level in different human cancer types." (PMID 37061713, 2023). "Deletion of the CENPO protein results in aneuploidy and aneuploidy chromosomal gains, which can lead to the development of disease or cancer." (PMID 37061713, 2023). "This study identified the difference in CENPO expression between cancer and normal tissues in patients with CRC." (PMID 35201521, 2022). "Small interference (Si) RNA transfer of CENPO protein will lead to the increase of aneuploidy and aneuploidy chromosomes, which will lead to disease or cancer." (PMID 35201521, 2022).
cancer (continued). "IHC staining used to identify the difference in CENPO expression between cancer and normal tissues in patients with CRC." (PMID 35201521, 2022). "We found that CENPO was significantly upregulated and was correlated with the clinical stage in several cancers, and the ROC curve analysis showed that CENPO may function as a diagnostic biomarker." (PMID 37061713, 2023). "Although previous studies have demonstrated the prognostic importance of CENPO in various types of cancer, there are few reports on whether aberrant CENPO expression influences immune cell infiltration." (PMID 37558987, 2023). "We analyzed CENPO expression in pan–cancer using the UCSC Xena database GDC–TCGA data." (PMID 37558987, 2023). "Therefore, we analyzed the relationship between expression levels of ICP genes and CENPO in multiple cancer types." (PMID 37061713, 2023). "Furthermore, CENPO is involved in the infiltration of immune cells into pan-cancer, making it a potential immunotherapeutic target in cancer therapy." (PMID 37061713, 2023). "Therefore, we conducted an in-depth analysis and evaluated the potential value of CENPO in the prognosis of cancer and immune response, particularly in LUAD." (PMID 37061713, 2023). "We preliminarily explored the potential mechanism of action of CENPO in LUAD, and CENPO could be used as an immunotherapeutic target and prognostic marker for pan–cancer, especially LUAD." (PMID 37558987, 2023). "Our results also show that CENPO plays an essential role in cancer immunity." (PMID 37061713, 2023). "CENPO was positively correlated with cell cycle, DNA damage, and DNA repair of most cancers." (PMID 37061713, 2023). "However, the direct role of CENPO in cancer and the detailed molecular mechanism are currently unclear, especially in CRC." (PMID 35201521, 2022). "Interestingly, CENPO was inversely correlated with the hypoxia and angiogenesis of most cancers." (PMID 37061713, 2023). "CENPO may be a potential pan–cancer biomarker and oncogene, especially in LUAD." (PMID 37558987, 2023). "According to ESTIMATE scores, there were positive correlations between CENPO expression and immune cell content in the TME of several cancers." (PMID 37061713, 2023). "The prognostic impact of aberrant CENPO expression on pan–cancer was investigated using the GEPIA database, and the impact of CENPO expression on the prognosis of LUAD patients was analyzed in conjunction with clinical data." (PMID 37558987, 2023). "Therefore, the correlation between CENPO expression and TMB or MSI in 33 common cancer types was analyzed." (PMID 37558987, 2023). "In pan-cancer, especially LUAD, CENPO may be a potential biomarker and oncogene." (PMID 37061713, 2023). "However, an investigation into the role of CENPO in pan–cancer is still lacking." (PMID 37558987, 2023). "However, the role of CENPO in pan–cancer and immune infiltration has not been reported." (PMID 37558987, 2023). "Furthermore, infiltration of CENPO and myeloid-derived suppressor cells (MDSC) showed a significant positive correlation, while T-cell NK infiltration showed a significant negative correlation in most cancers." (PMID 37061713, 2023).
infection (2 papers, 2023 to 2024). The state of being infected such as from the introduction of a foreign agent such as serum, vaccine, antigenic substance or organism. "The results indicate that the combination of ADIPOR1, CENPO, E2F2, and H2AC17 genes has the potential as characteristic genes for diagnosing and studying the acute phase of SFTS virus (SFTSV) infection." (PMID 37896902, 2023).
CENPO also shares sentences with these, for which no sentence is quoted: bladder cancer (3 papers); breast invasive carcinoma (1); endocrine system disorder (1); endometrial cancer (1); Fanconi anemia (1); gastrointestinal disease (1); lentivirus infection (1); mesothelioma (1); Obesity (1); prostate adenocarcinoma (1); renal cell carcinoma (1); sarcoma (1); systemic sclerosis (1); uveal melanoma (1).